BMAL1 (basic helix-loop-helix ARNT like 1)
Diseases named in the same sentence as BMAL1 in open-access papers (continued):
Sharing a sentence is not in itself a finding about the gene and the disease.
Obesity (continued). "In the liver, circadian mRNA and protein expression of clock genes such as PER1, PER2, BMAL1 and CLOCK and circadian-related metabolic regulators, such as AMPK, lipogenic enzymes, and gluconeogenic proteins are changed in response to HFD feeding, leading to obesity and insulin resistance." (PMID 36994336, 2021). "Without metformin, the absence of SIRT1 and mTOR block function of CLOCK and BMAL1 during obesity." (PMID 34356626, 2021). "Remarkably, deletion of Bmal1 in astrocytes in mice is sufficient to phenocopy the obesity, INS resistance, and glucose intolerance of Bmal1-/- constitutive KO mice, suggesting that robust astrocyte circadian rhythms could preserve whole-body homeostasis and metabolic health." (PMID 33815298, 2021). "Given the issue of PVH neuronal death in mice with γ2 deletion, these mice, despite providing evidence for PVH function in diurnal rhythms in metabolism and obesity, are not suitable to investigate whether γ2 diurnal expression mediates the role of BMAL1." (PMID 32732906, 2020). "The lack of inhibitory effect of REV-ERB ALPHA on BMAL1 expression in adipocytes from obese subjects might be due to impairment in the regulation of both genes in obesity." (PMID 25365257, 2014). "Dysfunction of BMAL1, CLOCK and PPARγ may lead to obesity and metabolic syndrome." (PMID 20706650, 2010). "Indeed, it seems that an activation of BMAL1, PPARα-induced, might have a direct link with high concentrations of retinoic acid (increased in metabolic syndrome) and reduced REV-ERBα levels in obesity and IR." (PMID 33142938, 2020). "In this study, we tested whether HF diet affects BMAL1 function in an insulin-dependent manner by analyzing BMAL1 activity in the liver as well as in several extra-hepatic tissues under conditions of diet-induced obesity with or without application of the thiazolidinedione, rosiglitazone (ROSI)." (PMID 29795456, 2019). "To determine the effect of the disrupted clocks on MetS components, we compared mRNA levels of Bmal1, Dec1, and Per1 in OSA patients with or without hyperglycemia, hypertension, hyperlipidemia, and obesity, which were considered as the major components of MetS." (PMID 36105285, 2022). "It is interesting that while ROSI restores BMAL1 recruitment in a target-specific manner in the tissues examined, prior studies reveal that while ROSI improves hepatic sensitivity, it neither reduces hepatic lipid deposition nor obesity in humans and rodents." (PMID 29795456, 2019). "In a time-course experiment with white adipose tissue biopsies from people with healthy weight or obesity or T2D, no variation in the rhythm and amplitude of core-clock (PER1, PER2, PER3, DBP, BMAL1, and CRY2), metabolic (PGC1), and clock-related (REVERB) genes could be observed in biopsy tissues." (PMID 37475884, 2023).
diabetes (60 papers, 2012 to 2026). "At the molecular level, tissue-specific disruption of any clock genes (i.e., CLOCK and BMAL1) regulating circadian rhythm accelerates the development of diabetes through pancreatic beta-cell loss and dysfunction." (PMID 38393018, 2024). "Disruption of CLOCK and BMAL1 was previously shown cause to hypoinsulinaemia and diabetes in mice, and changes in the synchronization of the beta cells, resulting in loss of pulsatile or first phase insulin secretion, are predictive for both T1D and T2D." (PMID 36589856, 2022). "The rs11022775T/rs7950226A BMAL1 haplotype was also nominally associated with an increased risk of diabetes in this cohort before correction for multiple testing (p = 0.007); this effect appeared to be driven by the rs11022775 SNP." (PMID 22485135, 2012). "Moreover, certain haplotypes of the Bmal1 gene have been demonstrated to be associated with an increased risk of diabetes and hypertension in human studies." (PMID 32964049, 2020). "Mutations of Clock and Bmal1 in mice resulted in hypoinsulemia and diabetes." (PMID 31555652, 2019). "For example, the genotyping of clock genes in 346 Greek pregnant women and their risk of diabetes was performed, detecting that the polymorphisms of Bmal1 rs7950226 and rs11022775 are associated with gestational diabetes mellitus (P = 0.025, OR = 1.46 and P = 4.455e − 06, OR = 2.64, resp)." (PMID 27313610, 2016). "However, colonic Bmal-1 mRNA expression was elevated in diabetic mice indicating that host-disease associated factors such as circadian misalignment and/or hormonal and metabolic changes because of diabetes can affect the gut microbiome rhythms." (PMID 31569518, 2019). "A recent study in mice showed that mutations in the genes encoding the CLOCK and BMAL1 transcription factors resulted in impaired glucose tolerance, reduced insulin secretion and defects in islet development, while ablation of the endogenous pancreatic clock resulted in the development of diabetes." (PMID 22485135, 2012). "In the present study, B12 modulated several core clock genes (Bmal1, Cry1, Cry2, Per1, Per3), while other genes were primarily affected by diabetes (Bhlhe40, Hif3a, and Nr1d1)." (PMID 41463345, 2025). "In pancreatic islet tissues, mutants of the circadian gene CLOCK and the protein BMAL1 show significantly impaired glucose tolerance, decreased insulin secretion, and pancreatic β-cell defects, leading to the onset of diabetes." (PMID 40115347, 2025). "Mechanistically, β-cell-specific Bmal1 overexpression enhanced the effects of nobiletin on pancreatic circadian rhythms and insulin secretion, highlighting the key role of Bmal1 in interventions in diabetes." (PMID 41155643, 2025). "In contrast, BMAL1 overexpression appears to provide renal protection in diabetes by promoting mitophagy via the HIF-1α/BNIP3 signaling pathway." (PMID 40594206, 2025). "They further found that mice with disrupted BMAL1 expression developed glucose intolerance, suggesting a direct genetic mechanism controlling diabetes as one measure of metabolic health." (PMID 39007272, 2024). "Diabetes alters the circadian rhythm of the corneal epithelium in mice, such that the expression of Clock, Bmal1, and Per2 is downregulated, and the expression of Cry1 and Rev-erbα is upregulated." (PMID 39062510, 2024). "It has been observed that BMAL1 knock-out mice show insulin resistance, diabetes, and impaired lipid homeostasis." (PMID 35733785, 2022). "Disruption of BMAL1 results in insulin resistance, diabetes, hyperlipidemia, increased body fat content and dysregulation of amino acid metabolism." (PMID 35733785, 2022). "Another study demonstrated the importance of BMAL1 in coordinating insulin secretion with the sleep–wake cycle and how BMAL1 ablation can trigger the onset of diabetes mellitus." (PMID 33807589, 2021). "Using RT-PCR, we examined two circadian genes Per2 and Bmal-1 in the colon to determine if diabetes affects the host circadian clock." (PMID 31569518, 2019).
diabetes (continued). "Disruption of the circadian timing system resulted in a significant decrease in glucose-stimulated insulin secretion, while disruption of the core clock components Clock and Bmal1 led to hypoinsulinemia and diabetes." (PMID 29385702, 2018). "rs6486121 and rs7950226 SNPs in BMAL1 have also been associated with hypertension and T2DM, respectively in 1304 individuals from 424 British T2D families from the Diabetes in Families (DIF) study collection." (PMID 26927084, 2016). "Diabetes downregulated Clock, Bmal1, and Per2 expression, upregulated Cry1 and Rev-erbα expression, reduced corneal epithelial mitosis, and increased leukocyte (neutrophils and γδ T-cells) recruitment to the cornea." (PMID 27611469, 2016). "Diabetes altered the circadian rhythm of the corneal epithelium in mice, such that the expression of Clock, Bmal1, and Per2 was downregulated, and the expression of Cry1 and Rev-erbα was upregulated." (PMID 27611469, 2016). "Bmal1 disruption also led to β-cell dysfunction and, consequently, to impaired glucose tolerance, reduced insulin secretion, and diabetes." (PMID 26927084, 2016). "In this study, we show that diabetes influenced the circadian rhythm in the expression of five core clock genes (Clock, Bmal1, Per2, Cry1, and Rev-erbα), as well as mitosis, in the normal murine corneal epithelium." (PMID 27611469, 2016). "It has been observed that Clock and Bmal1 knockouts in mouse pancreas produced hypoinsulinaemia and diabetes." (PMID 25837425, 2015). "Furthermore, diabetes exacerbates the suppression of BMAL1 expression, leading to a concomitant decline in mitophagy." (PMID 40594206, 2025). "Our data suggest that oscillations in mitochondrial calcium accumulation and oxidative damage in hippocampal neurons are indeed affected by O-GlcNAcylation of Bmal1, in addition, it provides solid evidence that Bma1l O-GlcNAcylation directly impairs cognitive function in diabetes." (PMID 39375536, 2024). "This modulation of Bmal1 function through O-GlcNAcylation of Bmal1 at S424 links glucose and Bhlhe41 upregulation in hippocampal neurons, implicating Bmal1 as a potential therapeutic target for the treatment of cognitive impairment in diabetes." (PMID 39375536, 2024). "Our study further confirmed that this strategy targeting site-specific O-GlcNAcylation on Bmal1 in hippocampal neurons may serve as a novel therapeutic approach for the treatment of cognitive impairment in diabetes." (PMID 39375536, 2024). "Disruption of Bmal1 in beta cells plays a notable role in the onset of diabetes." (PMID 36056774, 2022). "Therefore, in this study, we explored the mechanism by which the HDAC3-mediated Rev-erbα/BMAL1 pathway increases MI/RI vulnerability in diabetes and its relationship with mitophagy rhythm." (PMID 33414413, 2021). "However, the mechanism by which the HDAC3-orchestrated Rev-erbα/BMAL1 pathway increases MI/RI in diabetes and its relationship with mitophagy have yet to be elucidated." (PMID 33414413, 2021). "Bmal1 and its downstream regulation seems to play a crucial role in pancreatic regulation of metabolic processes, as Bmal1 knock out in mouse β-cells led to glucose intolerance and development of diabetes." (PMID 31379749, 2019). "Therefore, it is possible that the expression levels of Bmal1 and Clock in the skin are decreased in diabetes and that Aqp3 levels are decreased through the decrease in Dbp expression." (PMID 31382467, 2019). "Furthermore, mRNA expression of circadian clock genes such as PER1 and BMAL1 is dampened in peripheral leucocytes of diabetes subjects with poor sleep quality." (PMID 28352282, 2017). "Pancreas-specific Bmal1-null mice showed glucose tolerance that could lead to diabetes." (PMID 40024983, 2025). "In addition, we also analyzed the association between BMAL1 gene polymorphisms and blood glucose levels in normal blood glucose and prediabetes/diabetes participants, no significant results were found." (PMID 36732647, 2023).
diabetes (continued). "Here, we observed that the clock genes Rev-erbα, BMAL1, and C/EBPβ oscillations were altered in the hearts of rats with streptozotocin (STZ)-induced diabetes, with upregulated HDAC3 expression." (PMID 33414413, 2021). "In our study, the transcript levels of BMAL1, PER1, and PER3 were also significantly lower in the diabetes groups compared to the normal control group." (PMID 28352282, 2017). "More importantly, the mRNA levels of BMAL1 and PER1 genes were found to be significantly lower in the diabetes group with poor sleep quality compared to that with good sleep quality." (PMID 28352282, 2017). "BMAL1 mRNA levels increased in the younger diabetes participants but not in the older ones compared with the corresponding healthy participants." (PMID 38981930, 2024). "It has been suggested that Bmal1 can regulate the proliferation and matrix mineralization of BMSCs through the BMP signaling pathway or the bone homeostasis by the NF-κB pathway in type 2 diabetes mellitus." (PMID 38150082, 2024). "We speculated that the varying effect of diabetes on CLOCK and BMAL1 was due to the heterogeneity of histone modifications." (PMID 36012573, 2022). "Similar to the effects of diabetes on BMAL1 expression, neither morning exercise or night exercise altered the BMAL1 expression." (PMID 36012573, 2022). "The ability of insulin to restore circadian rhythm through BMAL1 and CLOCK genes may facilitate re-epithelialization, as these rhythms may be disturbed in diabetes." (PMID 32194500, 2020). "Collectively, our results demonstrated that targeting Bmal1 S424 O-GlcNAcylation with S424-pe may alleviate high-glucose-induced mitochondrial calcium overload and oxidative damage in hippocampal CA1 neurons and thereby improve cognitive function in diabetes." (PMID 39375536, 2024). "Such treatment led to a decrease in binding of Clock to Bmal1 and a downregulation of Bhlhe41 and Dnajb4 expression, resulting in NCLX upregulation and an improvement in mitochondrial calcium overload, hippocampal neuron dysfunction, and cognitive impairment in diabetes." (PMID 39375536, 2024). "In contrast, diabetes did not change the expression of another rhythmic molecule—BMAL1." (PMID 36012573, 2022). "In addition, diabetes and exercise may selectively or characteristically affect the heterodimer of CLOCK and BMAL1." (PMID 36012573, 2022). "However, insulin did not restore the circadian rhythm in Clock (factorial design ANOVA, P > 0.05) and Bmal1 (factorial design ANOVA, P > 0.05), with the analysis showing statistically significant differences between the insulin-treated diabetes and control groups." (PMID 27611469, 2016). "The mRNA expression of BMAL1, PER1, PER2, and PER3 in leukocytes was observed to be lower in non-diabetic individuals, as compared to those with diabetes." (PMID 37475884, 2023).
breast carcinoma (57 papers, 2013 to 2025). "Data analysis and experimental verification show that BMAL1, as a key circadian rhythm-related gene, is down-regulated in breast cancer and is associated with poor prognosis." (PMID 41228459, 2025). "Contrastingly, DNA methylation in BMAL1 CpG2 was associated with breast cancer (OR 1.23; 95% CI 1.03–1.47)." (PMID 39587706, 2024). "Another study implicated that BMAL1 knockdown led to increased F4/80 CAMs infiltration in breast cancer, correlating with worse patient prognoses." (PMID 38607733, 2024). "BMAL1 can play a role as a tumor suppressor in obese mice, inhibiting the growth of BRCA and lung metastases, and the down-regulation of BMAL1 was associated with an increased risk of breast cancer metastasis." (PMID 38189049, 2023). "Breast cancer tissues carrying a variant containing CT/TT genotypes had a reduced level of BMAL1 expression." (PMID 31739444, 2019). "Of particular interest, the SNP rs2279287 within the BMAL1 gene was found to be associated with a reduced breast cancer risk, among the carriers with the variant containing CT/TT genotypes than among those with the homozygous wild-type genotype (CC)." (PMID 31739444, 2019). "Our data at the RNA level reveals that in breast cancers some genes contributing to core clock mechanisms, such as that encoding BMAL1, become reduced." (PMID 30348208, 2018). "In the main effects analysis, CC carriers of rs4238989 and GG carriers of rs3760138 in the AANAT gene had increased risk of breast cancer, whereas TT carriers of BMAL1 rs2278749 and TT carriers of CLOCK rs3749474 had reduced risk." (PMID 23822714, 2013). "In summary, our data suggest that DNA hypomethylation in CRY1 and BMAL1 could be part of a causal chain from road traffic noise to breast cancer." (PMID 39587706, 2024). "We additionally investigated whether the BMAL1 gene was associated with survival in breast cancer patients using the Kaplan–Meier (KM) database." (PMID 32316196, 2020). "For example, Bmal1-deficient fibroblasts exhibit reduced sensitivity to DNA-damaging anticancer drugs, such as etoposide and daunorubicin, while Bmal1 knockout mutation in the breast cancer cell line MCF10A sensitizes to cisplatin-induced apoptosis." (PMID 32522976, 2020). "However, the exact mechanism of BMAL1’s effect on the risk of breast cancer needs to be further studied." (PMID 31346317, 2019). "With respect to both intensity and duration of night shift work for at least 5 yr, in subjects with at least four consecutive night shifts, increased risk of breast cancer was associated with variant alleles of BMAL1 (rs2290035, rs969485) and ROR-b (rs3750420)." (PMID 23822714, 2013). "Through lentivirus‐mediated shRNA technology, we established stable BMAL1 knockdown in human breast cancer cell lines (SKBR3)." (PMID 41031266, 2025). "In summary, overexpression of BMAL1 exerts an inhibitory effect on breast cancer cells by promoting apoptosis, suppressing proliferation, and downregulating glycolysis-related pathways." (PMID 41228459, 2025). "Collectively, our data support a model whereby melatonin upregulates the expression of BMAL1, which is associated with ALDH3A1, thereby affecting the glycolytic process and ultimately influencing the proliferation of breast cancer cells." (PMID 41228459, 2025). "The findings revealed that, consistent with expectations, overexpression of BMAL1 markedly decreased both the glucose uptake capacity and lactate production in breast cancer cells." (PMID 41228459, 2025). "To establish the role of circadian clocks in regulating breast cancer cell behavior, we used lentiviral shRNA for BMAL1, the essential clock factor, to disrupt cellular clock functions in rhythmic MCF-7 cells." (PMID 38319971, 2024). "In post hoc analyses, we evaluated the effect of categorized methylation in CRY1 (CpG1, CpG2, CpG4, CpG6, CpG12) and BMAL1 (CpG2, CpG6, CpG7) and breast cancer." (PMID 39587706, 2024).